PER3P1 (PER3 pseudogene 1)
Synonyms: PER4
Gene: Processed pseudogene on chromosome 7 (9,634,270 to 9,635,703, forward strand). Ensembl gene ENSG00000271077.
Diseases named in the same sentence as PER3P1 in open-access papers:
PER3P1 is named in the same sentence as 1 disease in open-access papers, as found by Europe PMC text mining. Sharing a sentence is not in itself a finding about the gene and the disease. The quoted sentences say what the papers report.
tumor (1 paper, 2025). "Gene expression analysis showed that PER3P1, among all PER family genes, exhibited the greatest reduction in expression in tumor tissues, with a decrease of 77% compared to control samples." (PMID 40556338, 2025).